PLIN4 (perilipin 4)
Diseases named in the same sentence as PLIN4 in open-access papers (continued):
Sharing a sentence is not in itself a finding about the gene and the disease.
cancer (10 papers, 2015 to 2025). A tumor composed of atypical neoplastic, often pleomorphic cells that invade other tissues. "Interestingly, most of these genes are linked with cancer processes (Pld1, Fam13c, Svbp, TMem192, Zc3h7a, RTP4, Naa30, Zgrf1, Slc33a1, Dnmt3b, Map6, Plin4, Eps8L2, Alg12, Capg and Tdp2)." (PMID 37700325, 2023). "The exploration of its specific functions on lipid droplets is still in its infancy, while some studies revealed that Plin4 might have a role in cancer progression." (PMID 36439875, 2022). "Those CNC variations associated with poor outcome (MUC5B, ZXDB, PLIN4, CCDC144NL, CNTNAP3B, and CCDC180) may probably facilitate cancer initiation and progression, and may be a new clue to study cancer metastasis and evolution." (PMID 29262625, 2017). "The high-throughput proteomics analysis revealed differential expressions of Acsl1, Plin1, Dbil5, Plin4, Col12a1, Col1a1, Col5a3, Col1a2, and Dcn, which are associated with the PPAR signaling pathway, protein digestion and absorption, and the protein glycan pathway in cancer." (PMID 36874004, 2023).
myopathies (2 papers, 2023 to 2025). "More recently, three unrelated families and one Chinese sporadic patient with PLIN4-related myopathy have been reported." (PMID 37176163, 2023).
cardiovascular disease (1 paper, 2022). "Phenotypic follow-up suggests that LoF of PLIN1, PDE3B, and ACVR1C favorably affects metabolic phenotypes (eg, triglycerides [TGs] and high-density lipoprotein [HDL] cholesterol concentrations) and reduces the risk of cardiovascular disease, whereas PLIN4 LoF has adverse health consequences." (PMID 34875679, 2022).
infection (1 paper, 2023). The state of being infected such as from the introduction of a foreign agent such as serum, vaccine, antigenic substance or organism. "Moreover, infection decreased expression of select proteins at the cellular level and increased expression of PLIN4, a protein previously characterized as a marker of OL stress." (PMID 37596606, 2023). "Additionally, infection-induced increase in PLIN4, a protein essential to lipid droplet stabilization, may reflect increased cellular accumulation of lipid." (PMID 37596606, 2023). "As observed in our previous experiments, Plin4 was upregulated by infection, but its expression was not significantly affected by GW2580 treatment." (PMID 37596606, 2023). "Furthermore, immunostaining for PLIN4 revealed it was, albeit not exclusively, co-localized to APC+ mature OLs and that the number of PLIN4-expressing mature OLs in the mPFC was increased by infection." (PMID 37596606, 2023).
metabolic disease (1 paper, 2024). A congenital disorder (due to inherited enzyme abnormality) or acquired (due to failure of a metabolically important organ) disorder resulting from an abnormal metabolic process. "In particular, mutations in PLIN1 and PLIN4 have been linked to many metabolic phenotypes, and loss-of-function heterozygous mutations in PLIN1 and PLIN4 positively and negatively, respectively, correlate with metabolic disease." (PMID 39297796, 2024).
neurodegenerative disease (1 paper, 2022). A disorder of the central nervous system characterized by gradual and progressive loss of neural tissue and neurologic function. "PLIN4 induction is required for deposition of intracellular lipid droplets and may precede lipotoxicity and neurodegenerative disease." (PMID 35031523, 2022).
PLIN4 also shares sentences with these, for which no sentence is quoted: diabetes (2 papers); diabetes mellitus type 2 (2); bladder cancer (1); breast tumor (1); colorectal cancer (1); demyelinating disease (1); desminopathies (1); endometrial cancer (1); experimental autoimmune encephalomyelitis (1); gastric adenocarcinoma (1); HCMV infection (1); Hypertension (1); lung carcinoma (1); metastatic cancer (1); multiple sclerosis (1); oculopharyngeal muscular dystrophy (1); peripheral neuropathy (1); rigid spine syndrome (1); sarcoma (1); vacuolar myopathies (1).